BDNF (brain derived neurotrophic factor)
Diseases named in the same sentence as BDNF in open-access papers (continued):
Sharing a sentence is not in itself a finding about the gene and the disease.
neurodegenerative disease (continued). "In contrast, in neurodegenerative disease, elevated BDNF mRNA was observed in astrocytes surrounding amyloid plaques, while GDNF mRNA was elevated in astrocytes of lesioned striatum in the 6-hydroxydopamine (6-OHDA) model of PD." (PMID 36768317, 2023). "For some time, the utilization of BDNF supplementation or direct treatment has been considered as a therapeutic approach for addressing neurodegenerative disease." (PMID 37626771, 2023). "Among them, BDNF plays a crucial role in the development and correct maintenance of brain circuits and synaptic plasticity as well as in neurodegenerative diseases." (PMID 37238659, 2023). "The therapeutic potential of BDNF treatment is also discussed, in the hope of discovering new avenues for the treatment of neurodegenerative diseases." (PMID 35743271, 2022). "While any promoter containing CRE sites would be targeted for ICER-associated inhibition of CREB promoted transcription, we chose BDNF promoters II and IV to study due to the connection between BDNF and neurodegenerative diseases." (PMID 35418836, 2022). "Decreased Nerve Growth Factor (NGF) and Brain-Derived Neurotrophic Factor (BDNF) levels have been described in neurodegenerative diseases." (PMID 36579579, 2022). "Accordingly, BDNF and GDNF have been identified as potential therapeutic targets in neurodegenerative diseases, and pre-clinical studies have reported the beneficial effects of the administration of BDNF and GDNF in PD models." (PMID 35204164, 2022). "A decrease in BDNF has been found in people with neurodegenerative diseases, and exercise has been shown to increase BDNF levels in the hippocampus which promotes learning and memory." (PMID 35783131, 2022). "Brain-derived neurotrophic factor (BDNF) is an abundant NT that modulates key brain and spinal cord functions, and defects in BDNF trafficking are associated with neuronal death, neurodegenerative diseases and in nerve injury." (PMID 35431786, 2022). "Exercise can prevent the specific down-regulation of BDNF in patients with neurodegenerative diseases." (PMID 36389059, 2022). "Apart from the expression changes observed at the early phase of AD, the effects of BDNF disturbance were also manifested at later stages of this neurodegenerative disease." (PMID 35269761, 2022). "Upregulation of BDNF/TrkB/CREB this classic neuroprotective pathway signaling inhibits neuronal apoptosis in neurodegenerative diseases." (PMID 35781287, 2022). "What are the changes that occur in the production and protective effects of BDNF in the pathological process of chronic ischemic brain injury (e.g., chronic hypoperfusion) and neurodegenerative diseases (e.g., AD and PD)?" (PMID 35814950, 2022). "Taken together, these data suggest that CADPS2 regulates presynaptic BDNF release in dopaminergic neurons, which is particularly relevant to PD and other neurodegenerative diseases." (PMID 36086934, 2022). "This complex regulation demonstrates the vitality and diversity of BDNF in supporting existing neurons after cellular insults in multiple neurodegenerative diseases." (PMID 35668928, 2022). "This review aims to describe recent efforts to understand the connection between the level of BDNF and neurodegenerative diseases." (PMID 35625880, 2022). "Recently, it has been shown that BDNF can reduce neuroinflammation, which is an important determinant in neurodegenerative diseases." (PMID 35334932, 2022). "A variety of activators for the BDNF/TrkB system were well examined, and the corroboration with such an agonist for TrkA is very interesting to approach the therapeutic strategy against neurodegenerative diseases." (PMID 35887075, 2022). "Decreased levels of neurotrophic factors, mainly BDNF and its receptors, are among the most common physiological changes in neurodegenerative diseases such as PD75–78." (PMID 36316416, 2022).
neurodegenerative disease (continued). "The change of BDNF functions can be observed in some neurodegenerative diseases, and there is evidence that the insufficient or decreased density of BDNF is an important cause of neuronal injury, apoptosis and the decline of neuronal synaptic plasticity." (PMID 35732706, 2022). "Numerous studies have focused on the efficacy of irisin in delaying the onset of neurodegenerative diseases, showing that increased irisin secretion promotes the release of brain-derived neurotrophic factor and reduces β-amyloid deposition in the hippocampus." (PMID 35634506, 2022). "Three main mechanisms by which exercise affects neurodegenerative diseases were summed up, including adult neurogenesis, brain-derived neurotrophic factor (BDNF) signaling, and short-chain fatty acids (SCFAs) metabolism." (PMID 36389059, 2022). "Fucoxanthin plays a crucial role in combating neurodegenerative diseases by decreasing proinflammatory factor production or increasing the neuroprotective expression of BDNF." (PMID 36499295, 2022). "A decrease in brain-derived neurotrophic factor has been found in people with neurodegenerative diseases, and exercise has been shown to increase these levels in the hippocampus, promoting learning and memory." (PMID 35783131, 2022). "Neurodegenerative diseases, including Parkinson’s disease and major depressive disorder (MDD), are linked to alteration in exosomal BDNF." (PMID 36231071, 2022). "Another factor that has been shown to decline with aging and be reduced in neurodegenerative diseases is brain derived neurotrophic factor (BDNF)." (PMID 35585026, 2022). "Lower blood BDNF is seen in neurodegenerative diseases, together with upregulation of pro-inflammatory cytokines in the brain, eventually causing neuronal death." (PMID 34439351, 2021). "Ample evidence has proclaimed that the role of miRNAs must be considered a vital aspect contributing to the pathogenesis of diverse neurodegenerative diseases as HD through targeting diverse molecules, such as BDNF." (PMID 35002691, 2021). "A large number of studies have shown that BDNF has shown potential therapeutic value in many neurodegenerative disease models and acute central nervous system damage." (PMID 35194435, 2021). "BDNF NAT, expressed from the opposite strand of the BDNF genomic locus, is known to regulate BDNF expression and can therefore be targeted to increase endogenous BDNF expression for the treatment of neurodegenerative diseases." (PMID 33953687, 2021). "Results obtained in many laboratories show that the BDNF level decreases during the ongoing neurodegenerative disease." (PMID 34768699, 2021). "BDNF delivery through AAV vectors has already been studied in neurodegenerative diseases like Alzheimer’s disease, showing a recovery in the neurodegenerative and behavioral phenotype of a mouse model of the disease." (PMID 33670433, 2021). "BDNF has been extensively investigated as a potential therapeutic tool for spinal cord injuries, neurodegenerative diseases and stem cell therapy with unclear results in human studies." (PMID 34909648, 2021). "Many previous studies have demonstrated that expression-level changes in specific NTFs, such as BDNF, CNTF, and glial cell line-derived neurotrophic factor (GDNF), are associated with the pathogenesis of neurodegenerative diseases, such as AD, PD, HD, and ALS." (PMID 33802760, 2021). "On the contrary, microglia can also secrete anti-inflammatory cytokines and some neurotrophic factors to ameliorate neurodegenerative disease, such as BDNF." (PMID 33821438, 2021). "Recent studies have demonstrated that decreased BDNF has a profound effect on neurodegenerative diseases in the obese population." (PMID 34501469, 2021). "In animal models of neurodegenerative diseases, therapy with BDNF in vivo and in vitro showed promising results." (PMID 34877406, 2021).
neurodegenerative disease (continued). "The activated BDNF/TrkB pathway exerts neuroprotective effects in many CNS diseases, including acute brain injury and neurodegenerative diseases." (PMID 34425835, 2021). "In fact, among the neurodegenerative diseases, HD is the one in which reduced BDNF levels best correlate with the onset and progression of the pathology." (PMID 33477654, 2021). "It seems that in these neurodegenerative diseases, there is a similar molecular mechanism leading to an alteration of intracellular BDNF trafficking and signaling." (PMID 33854544, 2021). "Despite the evident promise of BDNF AntagoNAT therapeutics in neurodegenerative disease, they are unable to cross the BBB thereby requiring delivery directly to the brain." (PMID 33953687, 2021). "BDNF has also been shown to be able to interact with oxygen radicals (ROS) whose imbalance is involved in the mechanisms of aging, neurodegenerative diseases and some neuropsychiatric disorders." (PMID 32397504, 2020). "Previous studies have shown that MSCs secrete brain-derived neurotrophic factor (BDNF) for neuronal protection, making it a promising candidate for the treatment of neurodegenerative diseases." (PMID 32977637, 2020). "Low levels of BDNF, NT-3, and TGFB have been associated with the pathogenesis of several neuropsychiatric and neurodegenerative diseases." (PMID 32483475, 2020). "Given the properties of BDNF, its application for treatment of neurodegenerative diseases, including PD, seems promising." (PMID 32050617, 2020). "Many studies have documented some evidence of a decreased expression of BDNF in different neurodegenerative diseases." (PMID 33293946, 2020). "The compensatory response of elevated BDNF expression in neurons in the early stages of the neurodegenerative disease was one possible explanation for elevated BDNF in these patients." (PMID 32932791, 2020). "BDNF which is also over-represented in the enrichment analysis of this study of neurodegenerative disease has been identified as a possible target sequence for hsa-miR-933." (PMID 32993798, 2020). "Previous attempts to use intravenous or intrathecal delivery of exogenous BDNF for the treatment of neurodegenerative diseases have failed." (PMID 32183860, 2020). "So, exploiting this information, it can be analyzed if ATF2 and hsa-miR-933 can play a neuroprotective role in neurodegenerative diseases by regulating their common target gene BDNF." (PMID 32993798, 2020). "Dysregulation of BDNF/TrkB signaling contributes to many pathological processes, including traumatic brain injury, brain ischemia, and neurodegenerative diseases." (PMID 31948437, 2020). "BDNF is presumed to be responsible for the survival and repair of neurons, and low plasma BDNF has been thought to be related to neurodegenerative diseases." (PMID 32932791, 2020). "Recent studies suggest that the stabilization of the BDNF autocrine loop is critical for prevention and treatment of neurodegenerative diseases." (PMID 32707633, 2020). "The levels of brain-derived neurotrophic factor (BDNF) are strongly reduced in different neurodegenerative diseases." (PMID 32731644, 2020). "Blood BDNF was assumed to be lower in patients with PD than in controls because of the nature of neurodegenerative diseases; however, prior research found heterogenicity to be remarkable." (PMID 32932791, 2020). "Another preventive and treatment strategy for neurodegenerative disease involves activating the production of brain-derived neurotrophic factor (BDNF)." (PMID 32707633, 2020). "In the context of neurodegenerative diseases, the influence of physical exercise has a direct effect on the brain-derived neurotrophic factor (BDNF)." (PMID 31937331, 2020). "A research field in continuous development focuses on studying the effects of exercise on BDNF level changes in healthy adult populations and in people affected by neurodegenerative disease." (PMID 33293946, 2020).
neurodegenerative disease (continued). "In neurodegenerative diseases such as AD, critically important growth factors including brain-derived neurotrophic factor (BDNF) and insulin-like growth factor 1 (IGF-1) are downregulated, suggesting a pivotal role in the pathophysiology of AD." (PMID 32090058, 2020). "The varying levels of BDNF in circulation of patients with neurodegenerative diseases once again support the idea of intrathecal administration of cells secreting BDNF so that it can act in the site of the injury." (PMID 32041109, 2020). "IL-1β has been shown to negatively regulate BDNF-dependent learning and memory in neurodegenerative diseases." (PMID 31948437, 2020). "A better understanding of the function and regulation of BDNF in different neuronal populations and corresponding synapses in the motor pathway will not only improve our understanding of neurodegenerative diseases." (PMID 32651187, 2020). "BDNF potentiation has also been demonstrated to enhance MN survival in vitro and in other neurodegenerative diseases." (PMID 31456666, 2019). "BDNF can mediate the neuroprotective effect of physical activity, both in the physiological process of aging and in neurodegenerative diseases." (PMID 31703409, 2019). "The STZ exposure inhibited hippocampal BDNF expression and signaling, which were consistent with previous studies that BDNF levels declined in animals or patients with neurodegenerative diseases in this region." (PMID 31040784, 2019). "Currently, many neurotrophic factors such as nerve growth factor (NGF) and brain-derived neurotrophic factor (BDNF) have been investigated for treating neurodegenerative diseases such as MS and AD." (PMID 31683745, 2019). "Several studies in both animals and humans have assessed the effects of physical activity on BDNF levels in psychiatric and neurodegenerative diseases." (PMID 30117106, 2019). "Since BDNF levels are decreased in demented patients, understanding the function of BDNF in memory processes is important to counteract neurodegenerative diseases." (PMID 31017891, 2019). "Several lines of evidence show that increased BDNF-TrkB is evident in a number of neurodegenerative diseases, including ALS." (PMID 31456666, 2019). "Neurotrophins, such as brain-derived neurotrophic factor (BDNF), have shown promise as neuroprotective agents, indicating their potential in therapeutic strategies for neurodegenerative disease." (PMID 31156376, 2019). "As a therapeutic target, the search for BDNF mimics for these diseases is similar to the idea of using stem cell therapy for abrogating stroke-induced neuroinflammation and related neurodegenerative diseases." (PMID 30999702, 2019). "On the other hand, BDNF contributes to synaptic plasticity and is protective in animal models of neurodegenerative diseases and brain injury." (PMID 30140412, 2018). "Variety of BDNF expression can directly affect NAA concentrations in the brain of patients with degenerative disease." (PMID 29980225, 2018). "Since NGF and BDNF play important roles in the development and maintenance of neuron function and survival, the link between these neurotrophic factors and neurodegenerative diseases is unsurprising." (PMID 30223579, 2018). "Next we asked whether proBDNF and BDNF could be detected in the CSF of AD patients and controls since this technique has been traditionally used to study the expression profile of different markers in alive individuals for the diagnostic and/or the prognostic of neurodegenerative diseases." (PMID 30428894, 2018). "Numerous experimental studies have indicated the effectiveness of BDNF against various brain pathologies, including hypoxic states and neurodegenerative diseases." (PMID 30081596, 2018). "Although we did not investigate changes in these neurotropic factors in the present study, we have found that Cur restores BDNF in other animal models of neurodegenerative diseases, which is under investigation." (PMID 28567323, 2017).
neurodegenerative disease (continued). "BDNF is a small protein widely expressed in the adult mammalian brain which promotes survival of neurons in neurodegenerative diseases, including PD." (PMID 28713483, 2017). "In this review, we described how BDNF and progranulin proteins are involved in psychiatric and neurodegenerative diseases." (PMID 26869919, 2016). "Measurement of circulating BDNF is considered of great interest as a possible biomarker of psychiatric and neurodegenerative diseases." (PMID 26539329, 2015). "Since BDNF and tau protein are critical factors both engaged in neuronal physiology activity and the development of neurodegenerative disease, the meaning of tau protein up-regulation by BDNF should be carefully interpreted." (PMID 24618580, 2014). "The roles of NGF and BDNF in neurogenesis also has been researched in some detail, and their potential use as a treatment for neurodegenerative disease has been investigated." (PMID 23536825, 2013). "Low levels of BDNF are found in patients with neurodegenerative diseases, including Alzheimer's disease and major depression." (PMID 22474595, 2012). "Here also, further corrobora-tion of the interplay of gonadal hormones and BDNF on psychiatric illnesses and neurodegenerative diseases is warranted." (PMID 21247257, 2012). "Several drug candidates, which were found to attenuate deleterious symptoms in various models of neurodegenerative disease, are reported to upregulate the expression of neurotrophic factors including BDNF." (PMID 21776259, 2011). "As mentioned, BDNF seems to be beneficial in the therapeutic approach to neurodegenerative diseases." (PMID 21776259, 2011). "There is a long-standing interest in brain-derived neurotrophic factor (BDNF) because of its implications in neurodegenerative diseases." (PMID 20109193, 2010). "For this study we have focused on BDNF and five other GPCR ligands that have been implicated in aging and neurodegenerative disease." (PMID 21179406, 2010). "Disruption of the neurotrophin brain-derived neurotrophic factor (BDNF) activity has been associated with aging and multiple neurodegenerative diseases that demonstrate oxidative pathological aspects." (PMID 21179406, 2010). "BDNF has a neuroprotective effect against many neurodegenerative diseases including AD." (PMID 40040308, 2025). "A future systematic review of systematic reviews with meta-analysis would be highly beneficial for exploring the nuanced differences between the impact of walking and other forms of exercise on BDNF concentrations in people with neurodegenerative diseases compared to healthy subjects." (PMID 40149776, 2025). "Understanding the mechanisms by which BDNF influence neuronal health could provide valuable insights for developing therapeutic strategies for neurodegenerative diseases." (PMID 39851517, 2025). "There is a frequently occurring polymorphism in relation to BDNF, which affects the predisposition to neurodegenerative diseases and the lack of the effect from aerobic physical exercise." (PMID 41562905, 2025). "Thus, BDNF is a key factor in brain health, with potential benefits for managing neurodegenerative diseases like MS." (PMID 40427596, 2025). "Consequently, BDNF has been explored as a potential therapeutic target for neurodegenerative diseases." (PMID 41583708, 2025). "Additionally, PPAR‐α agonists increase the expression of hippocampus BDNF, which reduces the progression of neurodegeneration in neurodegenerative diseases." (PMID 40040308, 2025). "Novel delivery methods using lipid nanoparticles or CRISPR-cas-based gene editing therapy has the potential to improve the precision and scalability of BDNF therapies across neurodegenerative diseases, representing a paradigmatic shift from a neuroprotective molecule to regeneration therapy." (PMID 40362507, 2025). "BDNF and related molecular signaling decrease in neurodegenerative diseases and aging." (PMID 40380033, 2025).